LAG3 (lymphocyte activating 3)
Diseases named in the same sentence as LAG3 in open-access papers (continued):
Sharing a sentence is not in itself a finding about the gene and the disease.
cervical cancer (continued). "In addition, we constructed a prognostic prediction model by combining key genes and clinicopathological parameters and found an important role for LAG3 in immunomodulation and tumor suppression in cervical cancer." (PMID 41025546, 2025). "Evidence suggests that elevated LAG-3 expression in tumor-infiltrating lymphocytes may correlate with impaired immune responses in cervical cancer." (PMID 40808954, 2025). "A key immune checkpoint gene, LAG3, was successfully screened and identified, which provides an important theoretical basis and a new idea for the development of novel immunotherapeutic drugs based on the LAG3 target (e.g., LAG3 inhibitor monotherapy or combination therapy) for cervical cancer." (PMID 41025546, 2025). "Using western blotting, we confirmed that LAG3 expression was reduced in cervical cancer tissues." (PMID 41025546, 2025). "Cervical cancer tissue samples, especially HPV-associated demonstrate high LAG-3 expression." (PMID 36077354, 2022). "LAG-3 may play an important role in the development of ovarian and cervical cancer." (PMID 36875956, 2023). "Co-stimulation molecules, including LAG-3, VISTA, ICOS, and OX40, serve as targets for combination drugs in patients with cervical cancer (NCT05864144, NCT03829501)." (PMID 39888529, 2025). "In this analysis of known and emerging inhibitory checkpoint receptors in patients with cervical cancer, we observed that in addition to an increase in PD-1 and TIGIT, the emerging receptors Tim-3, LAG-3 and NKG2A were likewise upregulated." (PMID 41300994, 2025). "Immunohistochemistry (IHC) analyses of specimens collected from various tumors, outside of this clinical trial, revealed LAG-3+ expression in most cancers, with frequency ranging from 52% (small cell lung cancer (SCLC)) to 100% (cervical cancer)." (PMID 37857711, 2023). "We observed that TIGIT was positively correlated with PD-1, LAG3, Tim3 on CD8+ T cells from PBMC of patients with cervical cancer." (PMID 35729552, 2022). "While LAG-3-targeted therapies remain in early development and have not yet gained regulatory approval for cervical cancer, preclinical studies have demonstrated promising therapeutic potential." (PMID 40808954, 2025). "Besides the widely researched target such as CTLA-4 and PD-1/PD-L1, some novel co-inhibitory immune checkpoints and their antibodies have also been explored in cervical cancer, such as TIGIT, LAG-3, and TIM-3." (PMID 36817443, 2023). "Therefore, we tested the expression of TIGIT with coinhibitory receptor PD-1, lymphocyte activation gene 3 protein (LAG3), and T cell immunoglobulin and mucin domain-containing protein 3 (Tim3) in the PBMC of cervical cancer." (PMID 35729552, 2022).
diffuse large B-cell lymphoma (18 papers, 2019 to 2025). "We have also recently demonstrated the importance of LAG-3 in cHL by showing that gene expression of LAG-3 was threefold higher in cHL compared to diffuse large B-cell lymphoma (DLBCL) cases." (PMID 34068762, 2021). "In diffuse large B-cell lymphoma (DLBCL), LAG-3 was detected by the positive staining in 39% of tumor cells, while TIM-3 expression was associated with poor prognosis." (PMID 32751706, 2020). "Importantly, these results are consistent with those reported in diffuse large B-cell lymphoma; a high proportion of TIM-3+, LAG-3+ and PD-1+ TIICs translated into poor survival." (PMID 35982052, 2022). "To date, a 89Zr-labeled anti-LAG-3 antibody (REGN3767) has been developed and is under clinical evaluation to image LAG-3 expression in patients with diffuse large B cell lymphoma (NCT04566978) and patients with solid cancer that are treated with the PD-1 blocking mAb, Cemiplimab (NCT04706715)." (PMID 34727262, 2021). "In the context of hematological cancers, LAG-3 expression has been correlated with the prognosis of CLL, acute myeloid leukemia (AML), follicular lymphoma (FL), and diffuse large B-cell lymphoma (DLBCL) patients." (PMID 39425148, 2024). "For example, it has been demonstrated that the upregulation of LAG-3 may contribute to the exhaustion of intrahepatic and peripheral hepatitis C virus (HCV)-specific CD8+ T cells and also of peripheral CD8+ T cells involved in the defense against diffuse large B-cell lymphoma (DLBCL)." (PMID 38893211, 2024). "Hence, dysregulated LAG-3 expression has been reported to negatively correlate with clinical outcome in a wide variety of cancers, including some of hematological origin, including CLL, follicular lymphoma (FL), diffuse large B-cell lymphoma (DLBCL) or acute myeloid leukemia (AML)." (PMID 33925565, 2021).
uveal melanoma (18 papers, 2019 to 2025). A melanoma derived from melanocytes of the uveal tract. "Analysis of The Cancer Genome Atlas (TCGA) datasets proved the presence of LAG-3 in uveal melanoma and its association with an increased rate of metastasis." (PMID 37004702, 2023). "As LAG-3 and its ligands display higher expression in patients with high-risk uveal melanoma, using anti-LAG-3 antibodies may be an effective approach for patients with metastatic uveal melanoma." (PMID 36997666, 2023). "LAG3, for example, was found to act as an immune checkpoint in uveal melanoma, and its expression in these patients was significantly higher compared to other immune checkpoints." (PMID 38418707, 2024). "Furthermore, this study found a high representation of lymphocyte activation gene-3 (LAG-3) and Galectin-3 in uveal melanoma." (PMID 37237550, 2023). "However, a previous scRNA-seq analysis provided a glimpse into primary and metastatic uveal melanomas ecosystems, and disclosed a regulatory T-cell phenotype, highlighting LAG3 as a potential candidate for immune checkpoint blockade." (PMID 37612741, 2023). "If further studies and clinical trials show promising outcomes, immunotherapy that targets the LAG3 checkpoint or the HDAC/MEK pathway may provide new insights into uveal melanoma treatment." (PMID 34195690, 2021). "The combination of nivolumab and relatimab (anti-LAG3 antibody; lymphocyte activation gene 3 is expressed in NK cells, B cells, and activated T cells and limits their proliferation and activation) is currently being evaluated in patients with unresectable or metastatic uveal melanomas (NCT03743766)." (PMID 38392052, 2024). "In addition, novel CTLA4-free combinations such as Relatlimab, a human IgG4 LAG-3-blocking antibody in combination with nivolumab may also play a role in uveal melanoma treatment in the future." (PMID 34298857, 2021). "Similarly, in uveal melanoma (UVM) and liver hepatocellular carcinoma (LIHC), CRABP2 expression is significantly correlated with seven of these immune checkpoint genes (LAG3, CTLA4, PDCD1LG2, HAVCR2, PDCD1, CD274, and TIGIT)." (PMID 39991584, 2025). "In uveal melanoma (UM), there was a negative correlation between LAG3 expression and invasion and metastasis." (PMID 38115039, 2023). "As previously discussed, the expression of additional immune checkpoint receptors such as LAG-3 or distinct expression levels of these immune checkpoints could also explain the unfavorable response rates to anti-CTLA-4 and anti-PD-1 therapies in uveal melanoma." (PMID 37004702, 2023).
bladder cancer (16 papers, 2019 to 2026). "Tebotelimab, a bispecific antibody targeting PD-1 and LAG-3, has been investigated in solid tumors but has yet to be explored in bladder cancer." (PMID 40647508, 2025). "Bladder cancer cells express immune ligands such as programmed death-1 receptor (PD-1), PD-L1, lymphocyte-activation gene-3 (LAG-3), TIM-3 and cytotoxic T-lymphocyte antigen-4 (CTLA-4) on its surface to evade immunological response and checkpoints." (PMID 34094648, 2021). "In bladder cancer, the abundance of LAG-3+ cells in the tumor stroma indicated an immunoevasive contexture and represented an independent predictor for poor OS." (PMID 33803936, 2021). "Besides, ERBB3, FGFR3, CTLA4, and LAG3 are also reported in some studies as potential therapeutic targets for bladder cancer." (PMID 34026819, 2021). "The bladder cancer samples were divided into high risk group and low risk group based on the median risk score, and the results of IHC indicated the positive frequencies of CTLA4 and LAG3 were higher in patients in high risk group." (PMID 34026819, 2021). "Our findings suggested that LAG-3 and TIM-3 could be new potential targets for ICIs in bladder cancer therapy." (PMID 40367012, 2025). "Our study indicated that LAG-3 and TIM-3 may serve as novel potential immune checkpoint inhibitors in bladder cancer treatment." (PMID 40367012, 2025). "Notably, PDLIM2 expression was strongly correlated with TIM-3 in bladder cancer and with PDCD1, CTLA4, GZMB, and LAG3 in KIRP." (PMID 35121770, 2022). "Though the signature was only significantly associated with ICI-related biomarkers like TNFRSF9, instead of CTLA4, LAG3, HAVCR2 and PDCD1, thus proving that the efficacy of immunotherapy still presents an underprivileged position within the treatment of bladder cancer." (PMID 34322391, 2021). "This study elucidates the immunogenic landscape of these rare bladder cancer subtypes, laying the groundwork for future trials using antibodies that are currently in clinical development to expand therapeutic options by including TIM-3, TIGIT, and LAG-3 into the immunomodulatory armamentarium." (PMID 40647508, 2025). "Our data indicated that bladder cancer patients with high TstcSig exhibited “hot tumor” characteristics, characterized by a higher proportion of infiltrating immune cells, elevated immune scores, and increased expression of immune checkpoint genes such as PDCD1, CDLA4, LAG3, and CD274." (PMID 39033098, 2024). "This study provides a comprehensive analysis of the intricate immune profiles of three relevant co-receptors—TIM-3, LAG-3, and TIGIT—in the most relevant non-urothelial subtypes of bladder cancer." (PMID 40647508, 2025).
clear cell renal cell carcinoma (16 papers, 2020 to 2025). "Specifically, LAG3 mRNA was expressed at a higher level in tumors than in normal tissues, and higher LAG3 mRNA levels were associated with poor prognosis in kidney clear cell carcinoma." (PMID 38062416, 2023). "Recent studies have shown that LAG3 DNA methylation is significantly associated with LAG3 expression of tumor cells and immune cell infiltration in clear renal cell carcinoma." (PMID 33767709, 2021). "Likewise, co-expression of PD-1, TIM-3, and LAG-3 in TILs of patients clear cell renal cell carcinoma (CCRC) has been associated with high risk of early progression." (PMID 36605214, 2022). "Emerging checkpoints like LAG-3 play a pivotal role in downregulating T-cell activation, and their expression has been associated with poor prognosis in various malignancies, including renal clear cell carcinoma (KIRC) and kidney renal papillary cell carcinoma (KIRP)." (PMID 40361336, 2025). "C1q-producing TAMs were associated with an immunosuppressed TME in clear cell renal cell carcinoma (ccRCC), characterized by high expression of immune-checkpoint molecules (PD1, LAG3, PDL1 and PDL2)." (PMID 40370471, 2025). "Renal clear cell carcinoma (KIRC), kidney renal papillary cell carcinoma (KIRP), and several other malignancies, as LAG3 expression has been associated with poor prognosis due to various cancers." (PMID 40361336, 2025). "In addition, the high densities of tumor-infiltrating C1q+ TAMs in clear cell renal carcinoma (ccRCC) patients are significantly associated with an immunosuppressive microenvironment, which is characterized by the high expression of immune checkpoints (i.e., PD-1, LAG-3, PD-L1, and PD-L2)." (PMID 37187751, 2023). "High expression of LAG3 correlates with a poor prognosis in renal clear cell carcinoma, primary central nervous system lymphoma, and muscle-invasive bladder cancer." (PMID 38062416, 2023). "Other studies have shown that soluble LAG3 (sLAG3) and sCD28 were negatively correlated with the cytolytic activity of T cells in clear-cell renal cancer." (PMID 38203670, 2023). "Methylation of LAG3 was strongly correlated with its expression and infiltrations of distinct immune cells in clear cell renal cell carcinoma." (PMID 34227253, 2021). "A correlative analysis in clear cell renal cell carcinoma demonstrated prognostic significance for LAG3 methylation and mRNA expression, with high LAG3 expression indicating adverse overall survival." (PMID 32861198, 2020). "Recently, LAG3 expression in clear cell renal carcinoma cell lines and a tumor cell-intrinsic LAG3 protein expression was reported." (PMID 32861198, 2020). "Moreover, soluble CD28 and LAG3 were found negatively correlated with cytolytic activity of T cells in clear cell renal cell carcinoma (r = − 0.33 and − 0.32, respectively)." (PMID 40659985, 2025). "In addition, DNA methylation of the Lag-3 gene correlated with LAG-3 expression by tumor and immune cells, immune cell infiltration, transcriptional activity, and overall survival in clear cell renal cell carcinoma." (PMID 34067904, 2021). "In addition, a recent report suggests a LAG3 expression by tumor cells as shown in clear cell renal cell carcinomas." (PMID 32861198, 2020). "In renal clear cell carcinoma, TRPV3 can induce the expression of immune checkpoints such as LAG3, CTLA4, PDCD1, and TIGIT, leading to the accumulation of immunosuppressive T cells in the tumor microenvironment." (PMID 41331166, 2025). "We discovered that ACSL3 is substantially associated with the immune checkpoint inhibitors PD-1, PD-L1, CTLA4, LAG3, and HAVCR2 in renal clear cell carcinoma." (PMID 36338658, 2022).
ovarian tumor (16 papers, 2015 to 2025). "The expression of PD-1, Tim-3, and LAG-3 has been previously observed in ovarian tumor tissues and ascitic fluid." (PMID 40870871, 2025). "In vivo studies indicate that CD8+ T cells from OT-1-LAG-3−/−Pdcd1−/− mice exhibit enhanced effector function and produce more inflammatory cytokines and suggest that LAG-3 and PD-1 synergistically promote immune tolerance in ovarian tumors." (PMID 36077354, 2022). "It was found that in recurrent ovarian tumors there was a higher gene expression of LAG-3, HAVCR2 (TIM3), TIGIT and CTLA-4 than in primary tumors." (PMID 36077354, 2022). "Dual blockade of PD-1 and LAG-3 can enhance T cell effector function, slow murine ovarian tumor growth, increase numbers of CD8+ T cells, and reduce the frequency of Tregs and MDSC in the peritoneal TME." (PMID 33123161, 2020). "The ovarian tumors showed high gene expression of LAG3 and HAVCR2 (TIM3) and enhanced levels of TIGIT and CTLA4 in recurrent tumors compared to primary tumors." (PMID 33352957, 2020). "LAG3 and PD-1 could co-express in human ovarian tumor antigen-specific CD8+T cells, leading to T cell dysfunction." (PMID 31708918, 2019). "While PD-1 and CTLA-4 blockade has revolutionized treatment in some malignancies, ovarian tumors frequently deploy multiple redundant checkpoint pathways, including TIM-3, LAG-3, and TIGIT, to evade immune attack." (PMID 40643516, 2025). "Several checkpoints were coexpressed in TILs isolated from an ovarian tumor mouse model, including PD-1, CTLA-4, and lymphocyte activation gene-3 (LAG-3)." (PMID 36189283, 2022). "We have previously shown that human ovarian tumor-infiltrating CD8+ T cells co-expressing high levels of LAG3 and PD1 are dysfunctional and that dual blockade of both PD1 and LAG3 restores T effector function compared with blockade of either PD1 or LAG3 alone." (PMID 26318293, 2015). "Curiously, CD8+ T cells infiltrated ovarian tumors have high TIGIT expression as shown in this paper, which may suggest ovarian tumors are a potential target for combination anti-LAG3 and anti-TIGIT therapy." (PMID 38086828, 2023). "We evaluated whether dual antibody blockade of both LAG3 and PD1 pathways would reduce the IE9mp1 ovarian tumor growth in C57BL/6 (WT) mice." (PMID 26318293, 2015). "Indeed, when stimulated with IE9mp1 ovarian tumor cells, less SHP1 and SHP2 were pulled-down by anti-PD1 antibody in the Lag3−/− cells." (PMID 26318293, 2015). "Together, these results indicate that dual LAG3 and PD1 blockade enhance antitumor immunity in the ovarian tumor microenvironment through increases T cell infiltration, elevated T effector function as well as reduction in infiltration by immunosuppressive Tregs." (PMID 26318293, 2015). "We first show that LAG3 and PD1 are co-expressed on both OVA-specific and non-specific T cells infiltrating murine ovarian tumors." (PMID 26318293, 2015).